SRSF1 (serine and arginine rich splicing factor 1)
Diseases named in the same sentence as SRSF1 in open-access papers (continued):
Sharing a sentence is not in itself a finding about the gene and the disease.
fatty liver disease (2 papers, 2023 to 2024). A reversible condition wherein large vacuoles of triglyceride fat accumulate in liver cells via the process of steatosis. "It would be interesting to explore in the future whether under certain circumstances SRSF1 expression/activity is diminished in human hepatocytes and if that is clinically relevant in the development of fatty liver disease." (PMID 36759613, 2023).
head and neck cancer (2 papers, 2013 to 2023). A primary or metastatic malignant neoplasm affecting the head and neck. "In head and neck cancer, reduction of core splicing factor expression caused by hypoxia (i.e., SF1, SRSF1, SRSF3, and SRSF7) results in nearly 90% of IR-affected genes displaying high retention of introns in hypoxic compared with normal cells." (PMID 37506056, 2023).
head and neck squamous cell carcinoma (2 papers, 2021). A squamous cell carcinoma that arises from any of the following anatomic sites: lip and oral cavity, nasal cavity, paranasal sinuses, pharynx, larynx, and salivary glands. "The results of GEPAI database analysis showed that SRSF1 was high expression in head and neck squamous cell carcinoma and positively correlated with the expression of LINC01296." (PMID 34195277, 2021).
Intellectual disability (2 papers, 2023 to 2024). "SRSF1 haploinsufficiency is responsible for a syndromic developmental disorder associated with intellectual disability." (PMID 39590469, 2024). "demonstrate that haploinsufficiency of SRSF1, which encodes a pre-mRNA splicing factor, causes a syndromic neurodevelopmental disorder with mild to moderate intellectual disability." (PMID 37071997, 2023).
lupus nephritis (2 papers, 2021 to 2025). Glomerulonephritis in the context of systemic lupus erythematosus. "Furthermore, a T cell-restricted Srsf1-deficient mice develops systemic autoimmunity and lupus-nephritis, whereas Srsf1 deletion in myogenic progenitors leads to defects in neuromuscular junctions." (PMID 34338635, 2021). "SRSF1-deficient mice were found to exhibit systemic autoimmunity and lupus nephritis, which may be due to the impaired ability of SRSF1 to inhibit T-cell activation by suppressing mTOR pathway activity and maintaining PTEN expression." (PMID 40129567, 2025).
lymphopenia (2 papers, 2021 to 2022). Reduction in the number of lymphocytes. "Increased apoptosis of peripheral T cells has long been discussed, where recent studies revealed an association between low expression of serine arginine-rich splicing factor 1 (SRSF1) and anti-apoptotic Bcl-xL gene in T cells and lymphopenia in patients with SLE." (PMID 34502409, 2021). "The low number of CD8 cells was not accompanied by CD4 lymphopenia, as shown by the decreased CD8/CD4 ratio in the spleen (7.7) and MLN (2.6, n=3) of Srsf1-cKO mice compared to WT mice (1.3 and 0.96, p=0.0009 and p<0.0001, respectively)." (PMID 36189299, 2022).
male infertility (2 papers, 2023 to 2024). The inability of the male to effect fertilization of an ovum after a specified period of unprotected intercourse. "Specific deletion of Srsf1 in mouse germ cells impairs homing of precursor SSCs leading to male infertility." (PMID 38271475, 2024).
myocardial infarction (2 papers, 2022 to 2024). Gross necrosis of the myocardium, as a result of interruption of the blood supply to the area, as in coronary thrombosis. "In the present study, we aimed to investigate the involvement of SRSF1 in myocardial infarction and unveil its anti-apoptotic role in cardiomyocytes." (PMID 39578852, 2024). "This study emphasizes the importance of alternative splicing in cardiovascular diseases and suggests the therapeutic potential of SRSF1 for cardiomyocytes apoptosis and myocardial infarction." (PMID 39578852, 2024). "Collectively, these results indicate that SRSF1 exert a protective effect on cardiac injury and inhibits apoptosis in the context of myocardial infarction." (PMID 39578852, 2024). "Despite these findings, the role of SRSF1 in cardiovascular diseases, especially myocardial infarction, remains limited." (PMID 39578852, 2024). "In this study, we found that the expression of SRSF1 was significantly down-regulated in the hearts of mice with acute myocardial infarction (AMI) and H9C2 cells exposed to H2O2." (PMID 39578852, 2024). "The TTC test showed a reduction in the size of myocardial infarction in SRSF1 over-expressed mice." (PMID 39578852, 2024). "To investigate the role of SRSF1 on apoptosis of cardiomyocytes, we established in vitro and in vivo experimental models by treating H9C2 cells with H2O2 (200 μmol/L) and performing acute myocardial infarction surgery on C57BL/6 mice." (PMID 39578852, 2024). "There may be hsa_circ_0001147/hsa-miR-204-5p/GPM6A axis, hsa_circ_0004771/hsa-miR-629-3p/SRSF1 axis, hsa_circ_0061276/hsa-miR-629-3p/SRSF1 axis, hsa_circ_ 0045519/hsa-miR-298/ANK2 axis and hsa_circ_0004561 hsa-miR-298/ANK2 axis regulatory relationship involved in myocardial infarction." (PMID 35872921, 2022). "Therefore, there may be hsa_circ_0001147/hsa-miR-204-5p/GPM6A axis, hsa_circ_0004771/hsa-miR-629-3p/SRSF1 axis, hsa_circ_0061276/hsa-miR-629-3p/SRSF1 axis, hsa_circ_0045519/hsa-miR-298/ANK2 axis, and hsa_circ_0004561 hsa-miR-298/ANK2 axis regulatory relationship involved in myocardial infarction." (PMID 35872921, 2022).
oral squamous cell carcinoma (2 papers, 2021 to 2022). "In order to explore the function of SRSF1 in oral squamous cell carcinoma, we constructed SRSF1 overexpression plasmid and siRNA." (PMID 34195277, 2021). "LINC01296 promotes malignant lesions in oral squamous cell carcinoma by binding to SRSF1 protein, which provides important experimental data and theoretical basis for the prevention, diagnosis, and treatment of oral squamous cell carcinoma." (PMID 34195277, 2021).
ovarian insufficiency (2 papers, 2023 to 2026). "For example, SRSF1 directly regulates the alternative splicing of premature ovarian insufficiency (POI)‐related genes in oocytes, whereas SRSF3 maintains transcriptome integrity through alternative splicing regulation." (PMID 41524182, 2026). "The conditional knockout (cKO) of Srsf1 in mouse oocytes impairs primordial follicle formation and leads to primary ovarian insufficiency (POI)." (PMID 36882745, 2023).
pancreatitis (2 papers, 2024). Inflammation of the pancreas. "In PDAC, the splicing factor SRSF1 was recently shown to induce pancreatitis, an event tightly associated with tumorigenesis." (PMID 38325381, 2024).
pulmonary fibrosis (2 papers, 2025). Chronic progressive interstitial lung disorder characterized by the replacement of the lung tissue by connective tissue, leading to progressive dyspnea, respiratory failure, or right heart failure. "This lncRNA plays a critical role in the pathogenesis of pulmonary fibrosis by interacting with and modulating the expression of Serine/arginine-Rich Splicing Factor-1 (SRSF1), a protein primarily involved in RNA splicing processes." (PMID 40782499, 2025). "For example, DACH1 (LncRNA) can inhibit the activation of lung fibroblasts and the excessive deposition of the ECM by binding to SRSF1 and suppressing the expression of SRSF1 and CTNNB1 proteins, which helps alleviate pulmonary fibrosis." (PMID 40427668, 2025).
steatosis (2 papers, 2023 to 2024). Increased lipid within the cytoplasm of cells. "The greatest decrease in SRSF1 expression within hepatocytes was observed at PN6, which coincided with the onset of damage and steatosis detected histologically." (PMID 36759613, 2023). "At postnatal day (PN) 10, SRSF1 HKO livers were highly pale and yellow in color, signifying severe fatty infiltration of the tissue, referred to as steatosis." (PMID 36759613, 2023).
ACTHomas (1 paper, 2019). "Interestingly, SRSF1 mRNA levels were directly correlated with the aberrant splicing variant SST5TMD4 in NFPTs (r: 0.425; p = 0.049), GHomas (r: 0.532; p = 0.002), and ACTHomas (r: 0.509; p = 0.026)." (PMID 31561558, 2019). "Indeed, our results demonstrated that SRSF1 positively correlated with the oncogenic splicing variant SST5TMD4 in NFPTs, GHomas, and ACTHomas, and also that RNU11, and RNU6ATAC correlated with SST5TMD4 in GHomas." (PMID 31561558, 2019).
adenoma (1 paper, 2016). A neoplasm arising from the epithelium. "Also, the median levels of all SFs except SRSF1 were significantly higher in CR-adenoma than in CRNM." (PMID 27282379, 2016).
AIDS (1 paper, 2016). A syndrome resulting from the acquired deficiency of cellular immunity caused by the human immunodeficiency virus (HIV). "In order to examine the relevance to PML of this inverse functional relationship between Pur-alpha and SRSF1, immunohistochemistry was performed on serial sections of AIDS-PML brain tissue samples obtained from Dr. Susan Morgello, Manhattan HIV Brain Bank, NNTC." (PMID 27257867, 2016).
anaplastic oligodendroglioma (1 paper, 2021). A WHO grade III oligodendroglioma with focal or diffuse malignant morphologic features (prominent nuclear pleomorphism, mitoses, and increased cellularity). "Further studies, involving a larger series of grade III anaplastic oligodendrogliomas, would be useful to better investigate the immunoexpression of SRSF1 among these neoplasms." (PMID 33925821, 2021).
colorectal tumors (1 paper, 2012). "Researchers identified alternative splicing of SLC39A14, a divalent cation transporter, in colorectal tumors and found it to be regulated by the Wnt pathway, probably through regulation of splicing factor SRSF1." (PMID 22682314, 2012).
cyst (1 paper, 2023). A sac-like closed membranous structure that may be empty or contain fluid or amorphous material. "Our results revealed that the number of double-positive cells was reduced in newborn cKO ovaries, suggesting that SRSF1 is essential for cyst breakdown and primordial follicle formation." (PMID 36882745, 2023).
diabetic nephropathy (1 paper, 2017). "Our in vivo data further identified a concomitant elevation of SRSF1 mRNA and MALAT1 in the kidney of STZ‐induced diabetic mice, suggesting MALAT1 and SRSF1, with associated disordered pre‐mRNA processing, contributed to the development and progression of diabetic nephropathy." (PMID 28444861, 2017). "In addition, we showed mRNA levels of SRSF1, one of the major pre‐mRNA splicing factors, were upmodulated at 12 weeks (P < 0.01), suggesting SRSF1 might also have an engagement in diabetic nephropathy." (PMID 28444861, 2017).
endometrial carcinoma (1 paper, 2023). A malignant tumor arising from the epithelium that lines the cavity of the uterine body. "The effect of SNORD14E on the FOXM1 exon VIIa skipping was rescued by knocking down SRSF1 in endometrial carcinoma cell lines, suggesting that SNORD14E recognized FOXM1 and promoted the FOXM1 exon VIIa skipping by recruiting SRSF1 in combination with SRSF1." (PMID 37667311, 2023).
ependymoma (1 paper, 2021). A WHO grade II, slow growing tumor of children and young adults, usually located intraventricularly. "2/15 (13%), ependymomas showed low SRSF1 levels (IRS < 6) and in the remaining 13/15 cases (87%), SRSF1 immunoexpression was completely absent (IRS = 0)." (PMID 33925821, 2021). "We found high SRSF1 expression levels in most oligodendrogliomas (15/21; 71%), SEGAs (4/5; 80%) and PXAs (3/4; 75%), an absence of SRSF1 staining in 13/15 (87%) ependymomas and in 10/15 (67%) PAs; the remaining ependymoma (2/15) and PA (2/15) cases showed weak SRSF1 expression." (PMID 33925821, 2021).
glomerular diseases (1 paper, 2017). "By shuttling between the nucleus and the cytoplasm, SRSF1 interacted with and activated mTOR to promote translation 22, 23, 48; dysregulation of the latter was sufficient to facilitate glomerular diseases." (PMID 28444861, 2017).
Hutchinson-Gilford progeria syndrome (1 paper, 2017). "The serine-arginine (SR)-rich splicing factor 1 (SRSF1) controls LMNA pre-mRNA alternative splicing, leading to the production of progerin (the truncated prelamin A protein produced in HGPS (Hutchinson-Gilford Progeria Syndrome) cells and during physiological aging)." (PMID 28806747, 2017).
Hydrocephalus (1 paper, 2021). Hydrocephalus is an active distension of the ventricular system of the brain resulting from inadequate passage of CSF from its point of production within the cerebral ventricles to its point of absorption into the systemic circulation. "In contrast, no cases of hydrocephalus were observed in either the Srsf1+/+ or Srsf1NRS/+ littermates." (PMID 34338635, 2021).
learning disabilities (1 paper, 2023). "In conclusion, we described a cohort of individuals with heterozygous variants in SRSF1, responsible for a syndromic form of DD characterized by learning disabilities with mild to severe ID and, to a variable extent, associated with skeletal anomalies and with cardiac or urogenital malformations." (PMID 37071997, 2023).
liver dysfunctions (1 paper, 2023). "Although SRSF1 HKO livers began to overcome Cre-mediated knockout early in postnatal development, these mice still displayed severe liver dysfunctions at the adult stages." (PMID 36759613, 2023).
Merkel cell carcinoma (1 paper, 2025). "The study reveals that PRMT5-mediated methylation of SRSF1 preserves full-length Tip60, sustaining Tip60-EP400 complex–dependent chromatin repair and survival in Merkel cell carcinoma, highlighting a therapeutic vulnerability." (PMID 40846633, 2025).
metastatic melanoma (1 paper, 2017). A melanoma that has spread from its primary site to another anatomic site. "For example the lncRNA MALAT-1 has been associated with splicing, binds to SRSF1, at least in kidney tissue, and is overexpressed in metastatic melanoma." (PMID 28653984, 2017).
myositis (1 paper, 2018). "In particular, the pro-inflammatory cytokine TNF-α has been shown to downregulate SRSF1 expression during myositis thus contributing to modify the splicing profile of autoantigen transcripts, including PM/Scl-100 and PM/Scl-75." (PMID 29510724, 2018). "Indeed, the decreased expression of the splicing factor SRSF1 has been shown to contribute to myositis through an altered selection of alternative 5′ splice sites on its target substrates." (PMID 29510724, 2018).
oligodendroglioma (1 paper, 2021). A well-differentiated (WHO grade II), diffusely infiltrating neuroglial tumor, typically located in the cerebral hemispheres. "The specificity of SRSF1 for oligodendroglioma was 100%, the sensitivity was 13.33% and the ROC was 0.57 (95%CI 0.48–0.65)." (PMID 33925821, 2021).
pancreatic ductal adenocarcinoma (1 paper, 2024). An infiltrating adenocarcinoma that arises from the epithelial cells of the pancreas. "Past studies suggest that SRSF1 could activate MAPK signaling, partially due to the upregulation of interleukin 1 receptor type 1 (IL1R1) through alternative-splicing-regulated mRNA stability to trigger pancreatic ductal adenocarcinoma (PDAC)." (PMID 38735973, 2024).
pituitary tumor (1 paper, 2020). A benign or malignant neoplasm affecting the pituitary gland. "SRSF1 participates in the pituitary tumor machinery regulating the isoforms generated from the DIO1 gene." (PMID 33261069, 2020).
progeria (1 paper, 2022). "MG132 treatment improves cellular HGPS phenotypes in vitro, and injection of the drug in the skeletal muscle of a mouse model of progeria (LmnaG609G/G609G) locally reduced SRSF-1 expression and progerin levels." (PMID 35203262, 2022). "Injection of MG132 into the skeletal muscle of our progeria mice model (LmnaG609G/G609G) locally reduced progerin and SRSF-1 expression levels." (PMID 35203262, 2022).
prostate tumors (1 paper, 2022). "The serine and arginine-rich splicing factor 1 (SRSF1) is an RNA-binding protein whose oncogenic function has been described in numerous forms of human cancers, including brain, lung, and prostate tumors." (PMID 35056447, 2022).
psoriasis vulgaris (1 paper, 2015). Plaque psoriasis is the most common presentation of psoriasis. "In addition, treatment with a TNFα inhibitor downregulated SRSF1 expression in peripheral blood mononuclear cells (PBMCs) from psoriasis vulgaris patients." (PMID 25658361, 2015).
renal failure (1 paper, 2014). "For the rest four hub genes, SRSF1, CAND1, SMURF1, and YWHAE, no previous report of their association with renal failure has been proposed before." (PMID 24997640, 2014).
Rett syndrome (1 paper, 2020). A severe neurodevelopmental disorder affecting the central nervous system. "We show that cold-induced RNA-binding proteins rescue the neurite outgrowth defects in Rett syndrome using neuronal morphology analysis, and we also reveal that SRSF1 and PTBP1 are required for energy expenditure in adipocytes using metabolic flux analysis." (PMID 32546682, 2020).
sarcoma (1 paper, 2015). A usually aggressive malignant neoplasm of the soft tissue or bone. "have demonstrated that slight SRSF1 overexpression is capable of inducing cellular transformation in immortalized rodent fibroblasts in vitro as well as inducing sarcoma formation in nude mice." (PMID 25845590, 2015).
squamous carcinoma (1 paper, 2012). "In order to extend these data, two other cell lines, namely the H1299 adenocarcinoma and the H2170 squamous carcinoma cells, were transfected either with a control plasmid or with a plasmid encoding a myc-tagged SRSF1 protein and subjected to G418 selection for 6 days." (PMID 23071587, 2012). "In this study, we investigated the status of SRSF1, SRSF2 and its phosphorylated form P-SRSF2, as well as of SRPK1 and SRPK2 in a series of 107 NSCLC, including 54 adenocarcinoma (ADC) and 53 squamous cell carcinoma (SCC)." (PMID 23071587, 2012). "Compared to these normal lung tissues, SRSF1 was overexpressed in 65% (70/107; p<0.0001 versus normal) of NSCLC, with almost the same frequency in adenocarcinoma (ADC; 34/54; 63%; p<0.0001 versus normal) and squamous cell carcinoma (SCC; 36/53; 68%; p<0.0001 versus normal)." (PMID 23071587, 2012).
squamous cell lung carcinoma (1 paper, 2012). A carcinoma arising from squamous bronchial epithelial cells. "Here, we demonstrate that not only SRSF1 but also SRSF2, SRPK1 and SRPK2 proteins are overexpressed in both adenocarcinoma and squamous cell lung carcinoma." (PMID 23071587, 2012).
Stroke (1 paper, 2021). Sudden impairment of blood flow to a part of the brain due to occlusion or rupture of an artery to the brain. "Interestingly, altered cytoplasmic distribution of SRSF1 has been reported within the infarcted area of stroke victims when compared to the contralateral area, implicating a role for the cytoplasmic localisation of SRSF1 in tissue repair after ischaemia." (PMID 34376242, 2021).
synovial sarcoma (1 paper, 2025). "Concomitantly, genes activated by SS18::SSX in synovial sarcoma were repressed, including HOX genes HOXC6, HOXA10 as well as SRSF1 and TYMS." (PMID 40804185, 2025).